MALAT1 (metastasis associated lung adenocarcinoma transcript 1)
Diseases named in the same sentence as MALAT1 in open-access papers (continued):
Sharing a sentence is not in itself a finding about the gene and the disease.
glioma (continued). "Based on inferred copy number variations (CNV), cells with elevated CNV levels were classified as glioma cells revealing three subpopulations: C0 MALAT1+ glioma cells, C1 AKAP9+ glioma cells, and C2 NUSAP1+ glioma cells." (PMID 39975552, 2025). "While MALAT1 has been reported to be overexpressed in gliomas and associated with pathogenesis and chemoresistance, the specific molecular mechanism by which MALAT1 influences AS of its targets in gliomas, has yet to be determined." (PMID 39915450, 2025). "MALAT1 (NEAT2) is associated with metastasis and drug resistance in gliomas and represents a promising therapeutic target." (PMID 41149459, 2025). "MALAT1 also aids in evading glioma cell death (apoptosis) by reducing the levels of Rap1B, a Ras-related protein, by acting upon miR-101." (PMID 38059120, 2024). "For example, it has been demonstrated that lncRNA MALAT1 promotes the expression of SRY-box transcription factor 2 (SOX2) by suppressing miR-129 to promote glioma stem cell viability, proliferative abilities, and tumorigenesis." (PMID 36819921, 2023). "A study on lncRNA MALAT1 showed that it is an important activator of autophagy and promotes glioma cell proliferation by sponging miR-101." (PMID 36899946, 2023). "MALAT1 is frequently overexpressed in IDH-wildtype gliomas and enhances resistance to TMZ administration by regulating the expressions of miRNAs." (PMID 36819921, 2023). "For example, METTL3 potentiates the stability of MALAT1 by m6A modification with the assistance of an RNA-binding protein, HuR, thereby facilitating the malignant progression in gliomas with IDH wild-type." (PMID 37927399, 2023). "On the other hand, lncRNAs such as MALAT1 and HOTAIR have been implicated as oncogenes, promoting glioma cell growth, invasion, and angiogenesis." (PMID 37444408, 2023). "The recent literature has found that METTL3 can promote the malignant progression of glioma by regulating the stability of MALAT1 and activating NF-κB." (PMID 36114893, 2022). "The expression level of lncRNA MALAT1 is significantly correlated with the overall survival of glioma patients, which can be used as a persuasive prognostic biomarker for glioma patients." (PMID 36530425, 2022). "MALAT1 depletion increased proliferation of glioma stem cells and inhibited the expression of Nestin and Sox2, two stemness markers." (PMID 35928868, 2022). "It has been reported that the expression of MALAT1 in glioma tissue is lesser than normal brain tissue." (PMID 35935338, 2022). "In this study, they measured the expression levels of miR-101, Rap1B mRNA, and MALAT1 in U87 and U251 glioma cells." (PMID 35071748, 2022). "MALAT1-mediated cell proliferation promotion was due to activation of ERK/MAPK signaling pathway in glioma cells." (PMID 35928868, 2022). "In the human glioma cell line and glioma xenotransplantation model, the knockout of the MALAT1 gene promotes cell proliferation and invasion." (PMID 35935338, 2022). "METTL3 can regulate MALAT1 stabilization through m6A modification, and it activates NF-κB activity to promote the malignant progression of glioma." (PMID 35012593, 2022). "It was revealed that the higher expression of MALAT1 in glioma tumors correlated with lower miR-124 expression." (PMID 35071748, 2022). "Silencing of MALAT1 in glioma cell lines reduced proliferation and enhanced apoptosis, while suppression of miR-101 or over-expression of Rap1B had the opposite effects on proliferation and apoptosis." (PMID 35071748, 2022). "MALAT1 is reported to be glioma suppressive through attenuating ERK/MAPK-mediated growth and MMP2 mediated invasiveness." (PMID 35372082, 2022). "The study reported MALAT1 damage the suppressive effect of miR-101 on glioma cell autophagy by acting as ceRNA through upregulation of miR-101 targeting STMN1, RAB5A, and ATG4D." (PMID 34303380, 2021).
glioma (continued). "MALAT1 also acts as a tumor promoter, enhancing the tumorigenesis of glioma stem cells via modulation of miR-129 and subsequent suppression of SOX2." (PMID 33980320, 2021). "MALAT1 knockdown suppresses glioma cell proliferation and induces apoptosis, together with downregulated CCND1 and MYC expression." (PMID 34316694, 2021). "MALAT1 was downregulated in glioma and is able to regulate levels of MiR124 in various diseases, including Parkinson’s disease." (PMID 33477898, 2021). "Stemness: MALAT1 overexpression promoted proliferation of glioma stem cells by enhancing SRY-related HMG-box (SOX)-2 expression via inhibiting tumor suppressor miR-129, which led to increased tumor proliferation and viability." (PMID 34322395, 2021). "In apparent contradiction, MALAT1 expression has been shown by others to be highly expressed in glioma tissue and cell lines." (PMID 34316694, 2021). "Apoptosis: MALAT1 knockdown increased apoptosis and expression of apoptotic regulators, including MYC and CCND1 (encoding cyclin D1) in glioma." (PMID 34322395, 2021). "Some researchers illustrated the aberrantly increased expression of MALAT1 in glioma tissues and cells, and the correlation with worse prognosis in glioma patients." (PMID 34308750, 2021). "Increased expression of miRNA-101 contributes to the downregulation of MALAT1; upregulation of MALAT1 acting as an endogenous sponge gene decreased the expression of miRNA-101 in glioma and liver fibrosis." (PMID 34200314, 2021). "MALAT1 reduced the sensitivity of glioma cell lines to TMZ by enhancing EMT and upregulating multidrug resistance-associated protein expression." (PMID 34316694, 2021). "Invasion and metastasis: Knockdown of MALAT1 suppressed migration and invasion of glioma cells via several mechanisms, such as inhibiting autophagy via regulating the miR-384/GOLM1 axis." (PMID 34322395, 2021). "For example, lncRNA MALAT1 enhances the activity and proliferation ability of glioma stem cells and promotes glioma tumorigenesis." (PMID 32420340, 2020). "In the latest study, lncRNA MALAT1 also acted as a miRNA sponge to regulate autophagy in glioma cells." (PMID 33029125, 2020). "In a prognostic meta-analysis of 40 studies, MALAT1 expression predicted poor overall survival in patients with glioma, with a significant pooled hazard ratio of 2.32 (95% CI, 1.64–3.27; p < 0.001)." (PMID 32650527, 2020). "In vitro experiments also showed that lncRNA Malat1 significantly promoted autophagy and proliferation of glioma cells." (PMID 33029125, 2020). "These experimental results demonstrated that lncRNA MALAT1 promoted autophagy and proliferation of glioma cells by regulating the Malat1-miR-101-STMN1/RAB5A/ATG4D network." (PMID 33029125, 2020). "A comparison between the U87 and U251 glioma cell lines and normal human astrocytes revealed that the cancer cell lines had higher levels of MALAT1, and it has been recognized as oncogenic in glioma." (PMID 32650527, 2020). "Recent studies reported that MALAT1 is one of the most significantly upregulated lncRNAs in various tumors, including gliomas." (PMID 31479414, 2020). "Recently, lncRNA MALAT1 was found to be highly expressed in glioma tissues compared with adjacent normal tissues, and its elevated expression was positively associated with the LC3-II level." (PMID 33029125, 2020). "It has been reported that lncRNA MALAT1 was highly expressed in glioma tissue and served as an indicator for poor prognosis in glioma patients; however, the regulatory mechanism of lncRNA MALAT1 in human glioma was rarely studied." (PMID 33029125, 2020). "First, MALAT1 expression was measured in 4 glioma cell lines (A172, T98G, U251, and U87); U251 and T98G cells demonstrated higher expression of MALAT1 and were used in subsequent experiments." (PMID 31648104, 2019). "To investigate the role of MALAT1 in regulating ZHX1 expression, we knocked down MALAT1 in glioma cell lines with short hairpin RNAs (shRNAs)." (PMID 31648104, 2019).
glioma (continued). "MALAT1 expression level is significantly up-regulated in glioma stem cells, this up-regulation enhances the viability and proliferation of glioma stem cells and promotes the occurrence of glioma tumors." (PMID 31304004, 2019). "Collectively, these findings provide evidence that MALAT1 contributes to glioma tumorigenesis and plays a crucial role in promoting its proliferation and progression." (PMID 31648104, 2019). "After we obtained glioma stem cells from glioma cells, qRT‐PCR was utilized to measure the expression level of MALAT1." (PMID 29808528, 2018). "The down‐regulation of MALAT1 and miR‐129 overexpression both suppressed glioma tumour growth via SOX2 expression promotion in vivo." (PMID 29808528, 2018). "MALAT1 expression in glioma stem cells was remarkably higher than compared with non‐stem cells (P < .0001)." (PMID 29808528, 2018). "MALAT1 play a tumor-suppressive role in glioma by attenuating ERK/MAPK-mediated growth and MMP2-mediated invasiveness." (PMID 29458374, 2018). "The decreased level of MALAT1 in glioma significantly increased tumorigenicity in both subcutaneous and intracranial human glioma xenograft models." (PMID 29458374, 2018). "According to the results, MALAT1 suppresses the viability of the glioma cells by down-regulating miR-155 and promoting the expression of FBXW7." (PMID 30583549, 2018). "After transfection with si‐MALAT1 (si‐MALAT1#1 or si‐MALAT1#2), the expression of MALAT1 in glioma stem cells significantly decreased (P < .01)." (PMID 29808528, 2018). "The meta-analysis is firstly to investigate the relationship between MALAT1 expression and prognosis of glioma as well as estrogen-dependent cancer by pooling eligible studies in multivariate model, which is different from previous meta-analyses." (PMID 30093838, 2018). "Accordingly, the proliferation and invasion ability of glioma cells was significantly enhanced by MALAT1 knockdown in glioma xenograft models, whereas MALAT1 overexpression had opposite effects." (PMID 30116729, 2018). "The mRNA expression of MALAT1 was significantly up‐regulated in glioma stem cells compared with non‐stem cells, while miR‐129 was significantly down‐regulated in glioma stem cells." (PMID 29808528, 2018). "MALAT1 enhanced glioma stem cell viability and proliferation abilities and promoted glioma tumorigenesis through suppressing miR‐129 and facilitating SOX2 expressions." (PMID 29808528, 2018). "The expressions of MALAT1, miR‐129 and SOX2mRNA in both glioma non‐stem cells and glioma stem cells were examined by qRT‐PCR assay." (PMID 29808528, 2018). "The impact of MALAT1 and miR‐129 on glioma stem cell proliferation was observed by CCK‐8 assay, EdU assay and sphere formation assay." (PMID 29808528, 2018). "As a glioma-suppressor, MALAT1 inhibits cell viability by downregulating miR-155 expression, and a similar mechanism was also observed in the “TUSC7-miR-23b” axis." (PMID 29458374, 2018). "Consistent with previous research results, our data demonstrated that MALAT1 was involved in glioma tumorigenesis as a tumour promoter." (PMID 29808528, 2018). "To explore the role of MALAT1 in TMZ resistance of glioma cells, we first established TMZ‐resistant GBM cell line U251 as described in Materials and Methods." (PMID 29479863, 2018). "Li et al9 found that MALAT1 expression was up‐regulated in glioma, promoting cell propagation and inhibiting cell apoptosis." (PMID 29808528, 2018). "Xenograft mice models were established by subcutaneously injecting glioma stem cells with different expression of MALAT1 and miR‐129." (PMID 29808528, 2018). "Overall, down‐regulation of MALAT1 or overexpression of miR‐129 suppressed glioma tumour growth in vivo." (PMID 29808528, 2018). "Microarray analysis results revealed that MALAT1 was significantly up‐regulated in glioma stem‐like cells." (PMID 29808528, 2018).
glioma (continued). "MALAT-1 knockdown significantly reduced MAPK/ERK signalling in gallbladder cancer cells, and in glioma, MALAT-1 acts as a tumour suppressor by attenuating ERK/MAPK mediated signalling." (PMID 29701689, 2018). "In summary, our research showed that MALAT1 was up‐regulated in glioma stem cells and acted as a tumour promoter in glioma progression." (PMID 29808528, 2018). "The effects of MALAT1 and miR‐129 on glioma tumour growth were further confirmed using xenograft mouse model." (PMID 29808528, 2018). "Three studies showed that the expression of MALAT1 is up-regulated in glioma, and two—that the expression is down-regulated." (PMID 30583549, 2018). "Conversely, overexpression of MALAT1 counteracted the significant repression of cell proliferation and invasion in vitro and in vivo, indicating a tumor-suppressive role for MALAT1 in glioma." (PMID 28187439, 2017). "MALAT1 was lowly expressed in glioma tissues, hence the function of MALAT1 was investigated using siRNA and overexpression vector in two glioma cell lines (U87 and U251)." (PMID 26938295, 2016). "In conclusion, overall data demonstrated the tumor-suppressive role of MALAT1 in glioma by attenuating ERK/MAPK-mediated growth and MMP2-mediated invasiveness." (PMID 26938295, 2016). "Stable RNA interference-mediated knockdown of MALAT1 in human glioma cell lines (U87 and U251) significantly promoted the invasion and proliferation of the glioma cells by in vitro assays." (PMID 26938295, 2016). "The growth of tumors from the MALAT1-overexpressed xenografts of glioma cell line was significantly slower compared with that of tumors formed from the control cells (P<0.01)." (PMID 26938295, 2016). "In another study, MALAT1 expression was shown to be elevated in glioma tissues when compared with adjacent normal brain tissue; increased expression was correlated with poorer overall patient survival." (PMID 26230711, 2015). "For example, metastasis-associated lung adenocarcinoma transcript 1 (MALAT1), prostate cancer associated non-coding RNA 1 (PRNCR1), prostate cancer gene expression marker 1 (PCGEM1), H19, and several new lncRNAs involve in glioma development." (PMID 26172293, 2015). "In glioma, MALAT1 was shown to be upregulated and served as an independent prognostic parameter for patient survival." (PMID 26252651, 2015). "Oncomine database entries revealed that MALAT1 overexpression has been observed in brain and CNS cancer as well as head and neck cancer." (PMID 23717670, 2013). "For example, MALAT1 promotes the proliferation and metastasis of invasive pancreatic cancer by stimulating autophagy and can also activate autophagy and promote cell proliferation in gliomas." (PMID 40297152, 2025). "In state 1, the C0 MALAT1-expressing glioma cells were the most prevalent." (PMID 39975552, 2025). "However, the expression of the lincRNAs XIST, MALAT1 and H19, which are m6 A-modified transcripts, increased in glioma stem cells." (PMID 40382536, 2025). "Notably, we identified three major glioma cell subpopulations (C0 MALAT1+, C1 AKAP9+, and C2 NUSAP1+), which were highly correlated with tumor malignancy." (PMID 39975552, 2025). "Moreover, MALAT1 abolished miR-101-dependent negative regulation of the autophagic program in glioma cells by sponging miR-101, thereby prompting cell proliferation." (PMID 38561330, 2024). "Notably, H19, MALAT1, PVT1, and SBF2-AS1 have been associated with temozolomide resistance in glioma patients." (PMID 36819921, 2023). "We found that several lncRNAs, namely, AL606760.2, H19, MALAT1, PVT1 and SBF2-AS1 may function as glioma risk factors, whereas AC068643.1, AC079228.1, DGCR5, FAM13A-AS1, HAR1A and WDFY3-AS2 may have protective effects." (PMID 36819921, 2023). "Furthermore, MALAT1 promotes glioma cell proliferation and TMZ resistance by decreasing miR-203 expression and increasing the expression of thymidylate synthase (TS), a potent cancer chemotherapy target." (PMID 36819921, 2023).
glioma (continued). "METTL3 promoted the stability of MALAT1 and enhanced the glioma progression." (PMID 36212476, 2022). "MALAT1 repressed viability of glioma cells via suppressing miR-155 in vitro." (PMID 35928868, 2022). "MALAT1 expression was linked to the WHO grade, tumor size and poor survival in glioma patients." (PMID 35928868, 2022). "MALAT1 is a widely expressed lncRNA with a length of 8000 nt that is abnormally expressed in numerous cancer types and plays an important role in the proliferation, invasion, metastasis, and angiogenesis of bladder cancer and glioma." (PMID 35110552, 2022). "Furthermore, MALAT1 was associated with progression of glioma tumors, but the exact mechanism of MALAT1 in glioma is still uncertain." (PMID 35071748, 2022). "However, MALAT1 was downregulated in glioma and endometrioid endometrial carcinoma, where it exerted tumor-suppressive effects." (PMID 35585970, 2022). "Furthermore, HuR was reported to be essential for METTL3-mediated stabilization of metastasis-associated lung adenocarcinoma transcript 1 (MALAT1), which subsequently activated nuclear factor kappa B (NFκB) in IDH-wildtype glioma." (PMID 35625706, 2022). "MALAT1 suppresses glioma cell viability by downregulating miR-155 and promoting FBXW7 expression." (PMID 34316694, 2021). "Moreover, MALAT1 is highly expressed in the nucleus, and it has been confirmed to play a suppressive role in the formation of gliomas by downregulating MMP2 and devitalizing ERK/MAPK signaling." (PMID 33450825, 2021). "MALAT1 has been proved to have a crucial role in the progression of multiple neoplasms such as lung, colorectal and gastric cancers, and shows a comparable regulatory role in glioma." (PMID 34178684, 2021). "Circulatory biomarker: Compared to healthy controls, glioma patients had lower serum MALAT1 levels." (PMID 34322395, 2021). "The variable reports of the expression patterns of MALAT1 in gliomas may be due to the complexity of ncRNA biology and glioma heterogeneity or the vagaries of assessing differential gene expression, which may apply more broadly." (PMID 34316694, 2021). "Similarly, among glioma cell lines, glioma stem cell lines showed either lower or higher MALAT1 expression than parental cells." (PMID 34322395, 2021). "Moreover, MALAT1 plays a tumor-suppressive role in glioma cells by sponging miR-155, which leads to F-box/WD repeat-containing protein 7 (FBXW7) expression, and its downregulation in glioma tissues is associated with poor survival." (PMID 34202078, 2021). "In addition, MALAT1 enhances progression of glioma cells via upregulation of Rap1B, STMN1, RAB5A, and ATG4D by sponging miR-101." (PMID 33980320, 2021). "Reciprocal repression between MALAT1 and miR-140 was demonstrated in human gliomas." (PMID 33546468, 2021). "Similarly, downregulation of MALAT1 enhances cell proliferation via activation of the MAPK pathway in glioma stem cells." (PMID 33980320, 2021). "MALAT1 overexpression in glioma tissues was positively correlated with grade and tumor size." (PMID 31479414, 2020). "It has been proposed that impaired expression of MALAT1 (metastasis associated lung adenocarcinoma transcript 1) regulates autophagy in different cancers such as RTB, HCC, glioma, and GC via modulation of miRNAs, miR-101, miR-124, miR-23b-3p, as well as miR-216b." (PMID 32517694, 2020). "LncRNA MALAT1 was reported to have malignant status and predicted poor prognosis in glioma." (PMID 32009853, 2020). "Knockdown of lncRNA MALAT1 could depress glioma cell autophagy, migration, and invasion, whereas inhibiting miR-384 could eliminate these effects." (PMID 33029125, 2020). "More importantly, the inhibition of autophagy by 3-MA alleviated MALAT1-induced glioma proliferation, suggesting that lncRNA MALAT1 could activate autophagy and eventually promote glioma proliferation." (PMID 33029125, 2020).